MIRLET7D (microRNA let-7d)
Synonyms: hsa-let-7d; LET7D; MIRNLET7D; let-7d
Gene: MicroRNA gene on chromosome 9 (94,178,834 to 94,178,920, forward strand). Ensembl gene ENSG00000199133.
Gene Ontology:
Biological process: miRNA-mediated post-transcriptional gene silencing
Cellular component: RISC complex
Homologues: Orthologues: chimpanzee ptr-let-7d (100% identical), dog MIRLET7D (100% identical), guinea pig MIRLET7D (100% identical), macaque MIRLET7D (100% identical), rabbit MIRLET7D (100% identical), pig ssc-let-7d (99% identical), mouse Mirlet7d (98% identical), rat Mirlet7d (98% identical), zebrafish mirlet7a-5 (66% identical), zebrafish mirlet7a-6 (63% identical), Drosophila melanogaster mir-let7 (49% identical). Paralogues in human: MIRLET7A1 (69% identical), MIRLET7F2 (67% identical), MIRLET7E (63% identical), MIRLET7F1 (63% identical), MIRLET7C (62% identical), MIR98 (61% identical), MIRLET7A3 (61% identical), MIRLET7I (60% identical), MIRLET7A2 (56% identical), MIRLET7G (56% identical).
Diseases named in the same sentence as MIRLET7D in open-access papers:
MIRLET7D is named in the same sentence as 7 diseases in open-access papers, as found by Europe PMC text mining. Sharing a sentence is not in itself a finding about the gene and the disease. The quoted sentences say what the papers report.
breast carcinoma (1 paper, 2024). "In breast cancer, reduced levels of Mirlet7d have been related to enhanced cancer hallmarks." (PMID 38473229, 2024). "Moreover, we have unpublished results demonstrating that Mirlet7d reduced cancer hallmarks in breast cancer cells by degradation of MAFG-AS1 and suppression of the JAK2/STAT2 signaling pathway." (PMID 38473229, 2024).
emphysema (1 paper, 2024). "In the present study, we established that the Mirlet7 family members encoded by the Mirlet7b/Mirlet7c2 and Mirlet7a1/Mirlet7f1/Mirlet7d clusters are downregulated in T cells from lungs of emphysema patients and emphysematous mice that were exposed to CS or nCB." (PMID 38722677, 2024). "Here, we show that overall expression of the Mirlet7 clusters, Mirlet7b/Mirlet7c2 and Mirlet7a1/Mirlet7f1/Mirlet7d, are reduced in the lungs and T cells of smokers with emphysema as well as in mice with cigarette smoke (CS)- or nCB-elicited emphysema." (PMID 38722677, 2024). "Consistently, the analogous murine Mirlet7b/Mirlet7c2 and Mirlet7a1/Mirlet7f1/Mirlet7d clusters, respectively, were similarly downregulated in pre-clinical emphysema models." (PMID 38722677, 2024). "Next, we elucidated Mirlet7b/Mirlet7c2 and Mirlet7a1/Mirlet7f1/Mirlet7d cluster expression (herein referred to as Mirlet7bc2 and Mirlet7afd, respectively) in murine models of CS- or nCB-induced emphysema, respectively." (PMID 38722677, 2024). "miRNA expression-based studies have shown frequent downregulation of members of the Mirlet7 family, including Mirlet7a, Mirlet7b, Mirlet7c, Mirlet7d, Mirlet7e, and Mirlet7f in human emphysematous lung tissue and in murine models of emphysema, but the mechanism(s) of action remain ill-defined." (PMID 38722677, 2024). "In support of our original hypothesis, the CD4+ T cell expression of Mirlet7a, Mirlet7b, Mirlet7d, and Mirlet7f were all inversely correlated with more severe emphysema distribution in the lungs as determined by Computed Tomography (CT) scan." (PMID 38722677, 2024). "We did not ascertain whether deletion of Mirlet7a1/Mirlet7f1/Mirlet7d cluster is an equally or more effective modulator of experimentally induced emphysema." (PMID 38722677, 2024).
oral squamous cell carcinoma (1 paper, 2024). "Recent studies have revealed that reduced Mirlet7d levels in oral squamous cell carcinoma are linked to enhanced epithelial-mesenchymal transition (EMT) and increased migratory and invasive capabilities of cancer cells." (PMID 38473229, 2024). "Additionally, Mirlet7d downregulation correlated with heightened chemoresistance in oral squamous cell carcinoma, underlining its crucial role in cancer progression and treatment response (left bottom)." (PMID 38473229, 2024).
cancer (2 papers, 2018 to 2024). A tumor composed of atypical neoplastic, often pleomorphic cells that invade other tissues. "MIRLET7A1, MIRLET7F1, MIRLET7D are microRNA genes which are involved in cancer and DNA damage response pathways." (PMID 30386687, 2018). "The presence of miRNAs like miR-29b, Mirlet7d, miR-9, miR-126-5p, and miR-584-3p in the nucleus and their diverse regulatory roles, ranging from direct gene silencing to influencing intricate signaling pathways in cancer, signify a paradigm shift in our understanding of miRNA biology." (PMID 38473229, 2024). "Conversely, increased Mirlet7d levels reversed EMT, reducing invasiveness and enhancing chemosensitivity in cancer cells." (PMID 38473229, 2024).
MIRLET7D also shares sentences with these, for which no sentence is quoted: Autoimmunity (1 paper); colitis (1); osteosarcoma (1).